TRGV3 (T cell receptor gamma variable 3)
Description:
V region of the variable domain of T cell receptor (TR) gamma chain that participates in the antigen recognition. Gamma-delta TRs recognize a variety of self and foreign non-peptide antigens frequently expressed at the epithelial boundaries between the host and external environment, including endogenous lipids presented by MH-like protein CD1D and phosphoantigens presented by butyrophilin-like molecule BTN3A1. Upon antigen recognition induces rapid, innate-like immune responses involved in pathogen clearance and tissue repair. Binding of gamma-delta TR complex to antigen triggers phosphorylation of immunoreceptor tyrosine-based activation motifs (ITAMs) in the CD3 chains by the LCK and FYN kinases, allowing the recruitment, phosphorylation, and activation of ZAP70 that facilitates phosphorylation of the scaffolding proteins LCP2 and LAT. This lead to the formation of a supramolecular signalosome that recruits the phospholipase PLCG1, resulting in calcium mobilization and ERK activation, ultimately leading to T cell expansion and differentiation into effector cells. Gamma-delta TRs are produced through somatic rearrangement of a limited repertoire of variable (V), diversity (D), and joining (J) genes. The potential diversity of gamma-delta TRs is conferred by the unique ability to rearrange (D) genes in tandem and to utilize all three reading frames. The combinatorial diversity is considerably increased by the sequence exonuclease trimming and random nucleotide (N) region additions which occur during the V-(D)-J rearrangements.
Synonyms: TCRGV3; V1S3
Tractability: Antibody: a drug acting on it is in phase 2 or 3 trials; UniProt places it where antibodies can reach, with high confidence; UniProt predicts a signal peptide or a membrane-spanning region; its Gene Ontology location is reachable by antibodies, with medium confidence.
Gene: T-cell receptor variable (V) gene on chromosome 7 (38,358,512 to 38,359,162, reverse strand). Ensembl gene ENSG00000211699.
Subcellular location: Cell membrane
Gene Ontology:
Molecular function: MHC protein binding; peptide antigen binding
Biological process: immune response
Cellular component: plasma membrane
Homologues: Orthologues: mouse Trgv7 (44% identical). Paralogues in human: TRGV5 (92% identical), TRGV1 (77% identical), TRGV4 (77% identical), TRGV2 (75% identical), TRGV8 (72% identical), TRGV11 (25% identical), TRGV10 (24% identical), TRGV9 (23% identical), TRGC1 (0% identical), TRGC2 (0% identical).
Diseases named in the same sentence as TRGV3 in open-access papers:
TRGV3 is named in the same sentence as 2 diseases in open-access papers, as found by Europe PMC text mining. Sharing a sentence is not in itself a finding about the gene and the disease.
TRGV3 shares sentences with these, for which no sentence is quoted: prostate tumors (1 paper); tumor (1).